TNNC2 (troponin C2, fast skeletal type)
Description:
Troponin is the central regulatory protein of striated muscle contraction. Tn consists of three components: Tn-I which is the inhibitor of actomyosin ATPase, Tn-T which contains the binding site for tropomyosin and Tn-C. The binding of calcium to Tn-C abolishes the inhibitory action of Tn on actin filaments.
Synonyms: FAP85; CFAP85; CMYO15; CMYP15; MYONRI
Tractability: Small molecule: a drug acting on it is in phase 2 or 3 trials; a structure with a bound ligand is known.
Gene: Protein-coding gene on chromosome 20 (45,823,214 to 45,833,745, reverse strand). Ensembl gene ENSG00000101470.
Subcellular location (Human Protein Atlas): Nucleoplasm; Vesicles
Pathways (Reactome):
Muscle contraction: Striated Muscle Contraction
Gene Ontology:
Molecular function: actin binding; protein binding; calcium ion binding
Biological process: regulation of muscle contraction; skeletal muscle contraction
Cellular component: troponin complex; cytosol
Genetic constraint (gnomAD): Loss-of-function variants: 14 observed, 20.91 expected, observed/expected ratio (o/e) 0.67, 90% interval 0.44 to 1.05. The upper end of that interval is the gene's LOEUF score, 1.05, which puts it in group 4 of 6, group 1 being the genes least tolerant of losing a copy. Missense variants: 163 observed, 227.4 expected, observed/expected ratio (o/e) 0.72, 90% interval 0.63 to 0.82. Synonymous variants: 81 observed, 80.84 expected, observed/expected ratio (o/e) 1, 90% interval 0.84 to 1.21.
Gene-disease validity (ClinGen):
ClinGen rates the evidence that TNNC2 causes each of these diseases.
hypertrophic cardiomyopathy (autosomal dominant): No Known Disease Relationship. A condition in which the myocardium is hypertrophied without an obvious cause.
Homologues: Orthologues: chimpanzee TNNC2 (100% identical), rat Tnnc2 (99% identical), guinea pig TNNC2 (99% identical), mouse Tnnc2 (99% identical), macaque TNNC2 (96% identical), pig TNNC2 (93% identical), dog TNNC2 (90% identical), tropical clawed frog tnnc2 (90% identical), zebrafish tnnc2.2 (79% identical), zebrafish tnnc2.1 (77% identical). Paralogues in human: TNNC1 (63% identical).
Diseases named in the same sentence as TNNC2 in open-access papers:
TNNC2 is named in the same sentence as 20 diseases in open-access papers, as found by Europe PMC text mining. Sharing a sentence is not in itself a finding about the gene and the disease. The quoted sentences say what the papers report.
cardiomyopathy (2 papers, 2021 to 2023). A disease of the heart muscle or myocardium proper. "Based on gene expression and histology, clusters 0, 2, and 4 are skeletal muscle due to the high expression of APOD, MB, TCAP, and TNNC2 with significant upregulation of contractile components and cardiomyopathy processes." (PMID 37370820, 2023).
congenital myopathy (2 papers, 2021 to 2025). "TNNC2 has been implicated in a novel congenital myopathy, TNNI2 and TNNT3 in distal arthrogryposis (DA), and TNNT1 and TNNT3 in nemaline myopathy (NEM)." (PMID 34502093, 2021). "Screening of patients with congenital myopathy for variants in TNNC2 is warranted." (PMID 34502093, 2021). "Thus, pathogenic TNNC2 variants occur and cause a mild congenital myopathy phenotype with patients surviving into adulthood." (PMID 34502093, 2021). "These hypo‐contractile molecular and cellular events, also present in TNNC2‐related congenital myopathy, have been related to hypotonia and muscle weakness." (PMID 40320982, 2025).
head and neck squamous cell carcinoma (2 papers, 2019 to 2021). A squamous cell carcinoma that arises from any of the following anatomic sites: lip and oral cavity, nasal cavity, paranasal sinuses, pharynx, larynx, and salivary glands. "Another example is the bioinformatics-based discovery indicating that PYGM and troponin C2, fast skeletal type (TNNC2), are significantly down-regulated in head and neck squamous cell carcinoma." (PMID 33924466, 2021).
myocarditis (2 papers, 2022). Myocarditis is a condition that is characterized by inflammation of the heart muscle (myocardium). "However, two patients with MIS-C had autoantibodies against Troponin-C2 (TNNC2), a protein enriched in skeletal muscle; neither of these patients had myocarditis." (PMID 35360001, 2022).
colon tumor (1 paper, 2022). "A subcluster of genes encoding proteases (PRSS33), protease inhibitors (R3HDML), and cytoskeletal factors (TNNC2) was overexpressed only in colon tumor tissues and resembled the expression pattern of LY6G6D." (PMID 35953834, 2022).
COVID-19 (1 paper, 2022). A disease caused by infection with severe acute respiratory syndrome coronavirus 2. "One patient had antibodies to both KLHL12 and TNNC2 which might have been due to an underlying autoimmune condition, or a predisposition to autoantibodies that was triggered by COVID-19." (PMID 35360001, 2022).
hypertrophic cardiomyopathy (1 paper, 2025). "The hypertrophic cardiomyopathy pathway contains upregulated genes like sarcoplasmic/endoplasmic reticulum calcium ATPase 1 (ATP2 A1), myosin light chain 3 (MYL3) and troponin C, skeletal muscle (TNNC2)." (PMID 40708816, 2025).
metastasis (1 paper, 2019). The spread or migration of cancer cells from one part of the body (where they first appeared) to another. "It was found that the down-regulation of PYGM and TNNC2 in HNSCC was positively associated with lymph node metastasis and advanced tumor stage, implying their potential role in HNSCC metastasis and progression." (PMID 31324732, 2019).
oral squamous cell carcinoma (1 paper, 2019). "Specifically, the protein level of TNNC2 in oral squamous cell carcinoma samples was 11.5-fold lower than that in normal tissues." (PMID 31324732, 2019). "It showed that our findings were consistent with this study and suggested that TNNC2 may be exploited as efficient biomarkers for oral squamous cell carcinoma both in mRNA and protein levels." (PMID 31324732, 2019).
cancer (5 papers, 2016 to 2024). A tumor composed of atypical neoplastic, often pleomorphic cells that invade other tissues. "Regarding the remaining DEPs, Myh4, Acta1, Tnnt3, Mb, Ttn, Actn2, Myh7, Myl1, Mybpc2, Myl3, and Tnnc2 are associated with several cancers." (PMID 39861068, 2024). "For instance, approximately 40% (238 out of 610) of tissue samples from cancer of the large intestines show overexpression of TNNC2 in the COSMIC database." (PMID 29416706, 2018). "From our perspective, the overall underexpression of PYGM and TNNC2 in various cancers may imply the role of them in cancer development and progression and further investigation was of great value." (PMID 31324732, 2019). "Furthermore, the genes encoding cTnC (TNNC1; Id: COSG56773), fsTnC (TNNC2; Id: COSG65631), and all three TnT isoforms (TNNT1, Id: COSG65275; TNNT2, Id: COSG67007; TNNT3, Id: COSG60869) are overexpressed in several cancer types according to the COSMIC database." (PMID 29416706, 2018). "Of note, in classical carcinomas, there was coamplification and overexpression of the R3HDML, TNNC2, and DUSP15 locus at chromosome band 20q11-13, suggesting functional cooperation between these coamplified genes." (PMID 35953834, 2022). "MRNA levels of PYGM and TNNC2 were significantly down-regulated in a majority of cancer types and a multiple of independent analyses on HNSCC illustrated the down-regulation of PYGM and TNNC2 in tumor samples." (PMID 31324732, 2019). "Through data mining in a variety of databases, we illustrated that PYGM and TNNC2 were remarkably underexpressed in HNSCC, implying their possible role in cancer progression." (PMID 31324732, 2019). "Among these fusion transcripts, GTF2E2-NRG1, TMEM66-NRG1, TNNC2-WFDC, and HEPHL1-PANX1 fusion transcripts were found in both primary carcinoma and liver metastases from the same patient." (PMID 27461012, 2016). "Since we have illuminated that the expression level of PYGM and TNNC2 was down-regulated in HNSCC samples, then we focused on whether mRNA expression of these genes was related to cancer grade or stage in individual patients." (PMID 31324732, 2019).
tumor (3 papers, 2015 to 2021). "Subsequently, we further validated the relative lower mRNA levels of PYGM and TNNC2 in HNSCC tissues compared with adjacent normal tissues and demonstrated that the down-regulation of PYGM and TNNC2 was positively associated with lymph node metastasis and advanced tumor stage." (PMID 31324732, 2019). "For example, we found that ATAD1, TBC1D9, and TNNC2 expression are all mediated by transcription factors ACTRT2, MMP23B, and TP73 and methylation sites around MMP23B and TP73; these transcription factors have known functions in tumor suppression or proliferation." (PMID 33684137, 2021). "However, there existed no findings about TNNC2 with any tumor type and we supposed that further studies are warranted to elucidate its potential functions in HNSCC carcinogenesis." (PMID 31324732, 2019).
TNNC2 also shares sentences with these, for which no sentence is quoted: actinomycosis (1 paper); dilated cardiomyopathy (1); distal arthrogryposis (1); gingival cancer (1); nemaline myopathy (1); oral cancer (1); osteosarcoma (1); Thrombocytopenia (1); tongue tumor (1).